PIM1 (Pim-1 proto-oncogene, serine/threonine kinase)
Diseases named in the same sentence as PIM1 in open-access papers (continued):
Sharing a sentence is not in itself a finding about the gene and the disease.
cancer (continued). "In addition to the regulation of apoptosis, the protein products of these genes are involved in signaling pathways that are associated with cancer development and progression, including NF-ĸB (BCL3, SPHK1, and PRKCZ) and c-MYC (PIM1 and BTG1)." (PMID 38731835, 2024). "There is little literature focusing on the differing isoforms of Pim-1; however, one study has identified that there may be subtle differences between their phosphorylation activities within the context of cancer." (PMID 37511341, 2023). "In addition, PIM1 overexpression activates the expression of transcription factors to promote epithelial-mesenchymal transition (EMT) in order to regulate cancer progression and metastasis." (PMID 36982538, 2023). "Moreover, Pim1 inhibitors showed significant anticancer effect against HER2 positive cancer cells through HER2 down-regulation." (PMID 36728746, 2023). "Additionally, Pim1 inhibition was proved to assist in drug resistance cancers by inhibition of the consequent phosphorylation and activation of major causing drug-resistant proteins." (PMID 36728746, 2023). "In order to rationalize the results of in vitro enzymatic assays and cellular activity in cancer cell lines of the most potent dual CK2-α/PIM-1 inhibitors with the highest selectivity factor (SI), comprehensive in silico enzyme–substrate docking calculations were performed." (PMID 37514177, 2023). "Furthermore, PIM1 is a known GBP1-interacting protein in cancer cells and is a pro-survival, proto-oncogene that negatively regulates other pro-apoptotic proteins." (PMID 37797010, 2023). "Another oncogene, PIM1, encoding a constitutively active serine/threonine protein kinase, was investigated for its functional roles in the viability and growth of HPV-driven cancer cells." (PMID 36479105, 2022). "Intriguingly, the PIM1 gene, encoding for the kinase PIM1, was one of the top upregulated genes in lung fibroblasts from aged mice, and its function was previously implicated in STAT3-mediated cell survival and cancer-associated fibroblast activation." (PMID 35167499, 2022). "Notably, sustained expression of PIM1 is critical for tumor cell survival in hypoxic conditions, as PIM inhibitors selectively kill hypoxic cancer cells." (PMID 36429128, 2022). "Besides for lncRNAs, the functions of serine/threonine-protein kinase pim-1 (PIM1) in multiple cancers have already been reported by researches." (PMID 33842552, 2021). "While analyzing multiple cancer disorders, we found highly variable expression among genes implicated in cancer: EEF1A1, GNAS, NPM1, PIM1, and RHOA are known oncogenes; H3F3A, PTPRC, SMARCB1, and B2M are possible oncogenes; and CASP8, JAK1, and PRKAR1A are known tumor suppressor genes." (PMID 34174938, 2021). "Aberrant elevation of Pim1 has been observed in many cancer types and reported to play a crucial role in tumorigenesis due to the interactions with numerous proteins participating in various signaling pathways involved in cell proliferation, survival, and drug resistance." (PMID 34267653, 2021). "In preclinical studies, PIM-1 overexpression may lead to cancer development in the following major ways; by inhibiting apoptosis, by promoting cell proliferation and also through promoting genomic instability." (PMID 32397108, 2020). "We conclude that PIM-1 overexpression is observed at high frequency in CTCs from mCRPC patients and this finding, in combination with AR-V7 expression in CTCs, suggests its potential role as a very promising target for cancer therapy." (PMID 32397108, 2020). "Furthermore, we discovered that some of the predicted target genes of Oroxylum indicum were associated with cancer, such as EGFR, PIM1, ESR1/2, and MAPK8/10." (PMID 32733583, 2020).
cancer (continued). "Moreover, the C‐dots disrupt DNA repair through BER pathway and inhibits cancer cell proliferation likely through mTOR, Pim‐1, EGFR, and DNA damage pathways." (PMID 31692950, 2019). "Collectively, these data demonstrate that PIM1 overexpression in ccRCC cells may be a cancer-promoting event in ccRCC." (PMID 29472550, 2018). "In our study, depletion of PIM1 attenuated ccRCC cell proliferation, colony formation, migration, invasion and angiogenesis, suggesting that PIM1 expression may be a cancer-promoting event in ccRCC." (PMID 29472550, 2018). "A clearer understanding of these events may provide insight into how PIM1 could be efficiently targeted for degradation in cancer therapy." (PMID 28620180, 2017). "miR‐15b transfection into cancer cells has been shown to lead to decreased expression of Bcl‐2, cyclin E and PIM1 proteins, providing additional mechanistic explanations of how miR‐15b might play an important role in the development drug resistance." (PMID 28145098, 2017). "The metabolic consequences of decreased miR-33 and subsequent increase in PIM3 and PIM1, therefore, might also influence the cellular and systemic responses to mTOR inhibitors in cancer and other disease settings." (PMID 29170467, 2017). "However, in these cancer types, PIM1 and PIM2 can be overexpressed in the same tumor, which suggests that there is only a partial redundancy among them." (PMID 28938604, 2017). "PIM1 is overexpressed in many human cancers and is a promising target for drug development." (PMID 28620180, 2017). "PIM1 has been suggested an attractive drug target in cancer." (PMID 29042609, 2017). "We selected four mRNAs that are well studied in cancer: PIM1, HIF1A, TNFα, and c-MYC34." (PMID 26926077, 2016). "Furthermore, in these cancer types, PIM1 and PIM2 can be overexpressed in the same tumors, which suggest that there is only a partial redundancy among them and share some common physiological properties." (PMID 27901106, 2016). "The prognostic value of PIM-1 levels in cancer tissues remains controversial." (PMID 27596051, 2016). "Given that Pim1 inhibitors are already being tested in ongoing human clinical trials for cancer, the results presented here may open a new venue of drug discovery for AD by developing more Pim1 inhibitors." (PMID 27412291, 2016). "Thus the data suggests that the measurement of the cellular PIM1 level is critical for the selection of the most appropriate chemotherapeutic agent during cancer treatment." (PMID 26993775, 2016). "Thus, PIM-1 protein levels were increased significantly in cancer tissues compared with tumour-adjacent tissues (P = 0.041)." (PMID 27596051, 2016). "Increased PIM1 expression could partly explain the strong resistance of these cancers to chemotherapy." (PMID 27901106, 2016). "Further studies are needed to investigate the prognostic value of PIM-1 in cancers." (PMID 27596051, 2016). "Pim1 has gained much attention due to its upregulation in a variety of cancers." (PMID 27412291, 2016). "Moreover, many cancers are targeted using Aurora kinase and Pim1 inhibitors for reducing tumor burden." (PMID 26861404, 2016). "A previous study shows that miR-33a interact with Pim-1 in cancer cells." (PMID 25971209, 2015). "On the other end, PIM-1 was also shown to be required for radioresistance in murine cancer models." (PMID 26555723, 2015). "Overexpression of PIM1, a serine/threonine kinase, has been identified recently in human cancers." (PMID 25834102, 2015). "Taking also into account that, besides CK2, it inhibits PIM-1 (a very important and innovative target in cancer therapy), CLK2, and, with lower efficacy, also DYRK1A, we believe that TDB displays good features to be considered for future clinical experimentation." (PMID 26558259, 2015). "Increasing evidence shows the important role of Pim-1 in many cancers." (PMID 25551195, 2014).
cancer (continued). "However, the knock-down of pim1 substantially reduced cellular proliferation and focus-forming ability, which are typical of cancer cells, compared with cells expressing a control shRNA (shControl#1)." (PMID 24860787, 2014). "Thus, overexpression of Pim-1 in cancer cells can substantially contribute to malignant transformation, tumor progression and poor prognosis." (PMID 25342548, 2014). "Oncogenic characteristic of PIM-1 makes it an attractive target for cancer therapy." (PMID 25040935, 2014). "Pim-1 has been suggested as an attractive therapeutic target for different types of cancers." (PMID 25342548, 2014). "Pim-1 staining was detected in the nucleus and cytoplasm of carcinoma cells." (PMID 25342548, 2014). "Thus, Pim1 is an attractive target for cancer therapeutics, and there has been growing interest in developing small-molecule inhibitors for Pim1." (PMID 23936194, 2013). "In several cancer tissues somatic Pim-1 mutants have been identified." (PMID 23755147, 2013). "In addition, knockdown of KLF5 in cancer cells increases their sensitivity to DNA damage and related cell death, which is associated with reduced BAD phosphorylation and downregulation of PIM1." (PMID 23755247, 2013). "PIM1 mRNA decay kinetics during mitogenic stimulation of cancer cell lines." (PMID 22413002, 2012). "PIM1 is believed to be important for carcinogenesis because expression of this gene can lead to genomic instability and the preservation of potentially cancer-producing genomic alterations by promoting cell survival under conditions in which these alterations would not be normally tolerated." (PMID 22912571, 2012). "Efforts to improve the efficacy of this compound could lead to a potentially important way to target MYC/Pim1-expressing cancers." (PMID 20515470, 2010). "Furthermore, the inhibition of Pim-1 function by treatment with Pim-1 siRNA, Pim-1 inhibitors or Pim-1 mAb sensitizes cancer cells to chemotherapy." (PMID 21143989, 2010). "As many cancer-related genes have been linked to the development of polyploidy, for example MYC, APC, Pim-1, BRCA2, and Aurora-A, our model may reflect an actual pathway for tumor initiation." (PMID 18596907, 2008). "Humans are presently not known to carry an activated Pim1 gene, but other inherited gene defects are known that predispose carriers to develop cancer." (PMID 15538947, 2004). "Both PIM1 and ROCK2 promote cell migration in cancer, and there may be some associations." (PMID 36982538, 2023). "In particular, the search for inhibitors simultaneously targeting PIM-1 isoforms is of great interest because it opens new horizons toward the discovery of new chemicals capable of therapeutically modulating many biochemical pathways involved in the emergence and development of various cancers." (PMID 36970406, 2023). "However, little is known about the importance of PIM1 in cancer stem cells." (PMID 34681783, 2021). "One aspect of this differential activity may be influenced by heterogeneous binding partners, such as the findings that GBP1 interacts directly with proto-oncogene serine/threonine kinase 1 (PIM1), a marker of disease progression and treatment resistance in ovarian and other cancers." (PMID 32117203, 2019). "We could use PIM1 inhibitors or antibody against IL-6 to explore the anti-cancer effect." (PMID 30989585, 2019). "Therefore, inhibition of PIM-1 activity is an emerging approach for cancer therapy." (PMID 29483938, 2018). "To assess the effect of currently available therapeutic inhibitors targeting GBP1, we used NSC756093 that interrupts the interaction between GBP1 and proto-oncogene serine/threonine-protein kinase (PIM1), the inhibition of which could potentially revert paclitaxel resistance in cancer cells." (PMID 30303482, 2018).
cancer (continued). "The PIM kinase family consists of three constitutively active members, namely, PIM1, PIM2 and PIM3, which encode serine/threonine kinases with a broad range of cellular substrates that have been identified as oncogenes in multiple human malignant solid tumours." (PMID 29472550, 2018). "In spite of these challenges, future investigation of the role played by this regulatory mechanism in influencing the oncogenic function of PIM1 may provide a deeper understanding of the relationship of PIM1 to cancer development together with potential ideas for exploitation." (PMID 28620180, 2017). "To date, the antiapoptotic genes OLFM4, SIRT1, PIM-1, and DOCK3, the tumor suppressor PTEN, the cell proliferation and invasion genes CITRON and CLDN10, and FGF9 expressed by cancer-associated fibroblasts have been reported as potential targets for miR-486/miR-486-5p in malignant disease." (PMID 26895105, 2016). "In addition, we report evidence that PIM1 level may be relevant to assess the sensitivity of cancer cells to chemotherapeutic drugs that induce ribosomal stress." (PMID 26993775, 2016). "Thus, one must be cautious when selecting PIM-1 inhibitor for cancer therapeutic intervention." (PMID 25040935, 2014). "Notably, in several cancer tissues somatic Pim-1 mutants have been identified." (PMID 23755147, 2013). "Interestingly, in some cases, cancer-associated fibroblasts were positive for pim-1 expression, whereas in other cases they were pim-1 negative." (PMID 24116137, 2013). "Surprisingly, Pim1 overexpression and Pten loss in the untreated animals did not seem to cooperate, although 60% of the animals displayed high grade mPIN lesions, none progressed to carcinoma." (PMID 23565217, 2013). "PIM kinases, including PIM1, PIM2, and PIM3, are serine/threonine kinases frequently overexpressed in tumors and contribute to cancer cell proliferation, survival, and metastasis." (PMID 41199316, 2025). "In OS and HCC, under-expressed miR-1294 inhibits cancer cell apoptosis by upregulating pyruvate kinase M2 (PKM2) in OS and TEA domain transcription factor 1 (TEAD1) and pim-1 proto-oncogene in HCC." (PMID 37303740, 2023). "The 6 up-regulated genes (IL-20, CLK1, SORBS2, ERG1, PIM1, SNORD3A) are involved in cancer development." (PMID 38033043, 2023). "All the most up-regulated genes (IL-20, CLK1, SORBS2, ERG1, PIM1, SNORD3A) are involved in cancer development." (PMID 38033043, 2023). "Top up-regulated genes related to cancer were: (i) IL-20, CLK1, SORBS2, ERG1, PIM1, SNORD3A for normal FHC cells and (ii) TSLP, BHLHA15, LAMP3, ZNF27B, KRT17, ATF3 for cancerous HT29 cells." (PMID 38033043, 2023). "PIM1 and PIM3 can phosphorylate pro-apoptotic BAD at Ser-112 to deactivate it and thereby promote cancer cell survival and progression." (PMID 37943821, 2023). "Silencing or pharmacological inhibition of PIM1 results in MYC-related tumor inactivation, suggesting an essential role of PIM1 for MYC-driven cancer." (PMID 36969025, 2023). "PIM kinase transcripts, particularly PIM1 and PIM3, have also been shown to be regulated by microRNAs in cancer." (PMID 35326457, 2022). "CRISPR-Cas9-mediated exchange of PIM1 resulted in cell cycle arrest and apoptosis in HPV-driven most cancers." (PMID 36479105, 2022). "Others have shown that PIM1 and PIM2 mRNA expression correlated with mRNA expression of CD44 and CD133, two markers of glioblastoma cancer stem cells." (PMID 35892829, 2022). "miR-1 targets several cancer-related molecules, such as Slug, PI3KCA, FoxP1, Pim-1, HDAC4, CCDN2, and CXCR4, indicating that miR-1-3p regulates the expression of several oncogenic pathways." (PMID 35804872, 2022). "Several oncogenic targets of STAT3 have been recently identified such as c-myc, c-Jun, PLK-1, Pim1/2, Bcl-2, VEGF, bFGF, and Cten, and inhibitors of STAT3 have been developed for cancer prevention and treatment." (PMID 33435349, 2021).
cancer (continued). "In cancer, STAT3 promotes the expression of the provirus integration site for Moloney murine leukemia virus’ Pim1, a proto-oncogene serine/threonine-protein kinase." (PMID 34067108, 2021). "HSP90AA1, a 90-kDa heat shock protein, is an important target for cancer treatment because it can stabilize several cancer-related client proteins essential for tumor progression, such as AKT, PIM1, and HIF1A." (PMID 34194515, 2021). "Q-PCR was used to reveal that the transcriptional levels of STAT3-supporting cancer cell-intrinsic hallmarks, including BCL2, MMP9, HIF-1α and PIM1, were all decreased with SPATS2 knockdown in both MHCC-97H and HCC-LM3 cell lines." (PMID 33391405, 2021). "And we also revealed PIM1 inhibition as a new strategy to target at cancer stem cells population and RUNX3 was essential to the anti‐BrCSC effect of PIM1 inhibition." (PMID 32307917, 2020). "Many H3S10-kinases, including MSK1/2, PIM1, CDK8 and AURORA kinases, have been long considered targets in cancer therapy." (PMID 33054831, 2020). "PIM1 was only overexpressed in chromophobe RCC in our analysis, but its overexpression has been reported in many cancers, including RCC, and it has been shown to be a promising therapeutic target using RCC cell lines." (PMID 30863721, 2019). "In these networks, PTGS2, VDR, RHOB, PIM1, HSPA1L, HSPA1A, and SPHK1 were used as targets for cancer drug development, previously." (PMID 30842898, 2019). "The PIM1, PIM2, and PIM3 serine/threonine kinases play a role in the proliferation and survival of cancer cells." (PMID 31073371, 2019). "We also demonstrated that downregulation of PIM-1 increased the sensitivity of PDAC cells to erlotinib, enhanced erlotinib-induced apoptosis, and decreased cancer stem cell marker expression." (PMID 27596051, 2016). "miR-486 has been shown to participant in general tumorigenesis by targeting the anti-apoptotic OLFM4, SIRT1, PIM-1 and protumorigenic ARHGAP5 in various types of cancer." (PMID 27167342, 2016). "PIM-1 could induce fibroblast cells to secrete extracellular matrix, collagen 1A1, chemokine CCL5, and platelet‐derived growth factor receptor to enhance the ability of fibroblasts to differentiate into myofibroblasts and express known markers of cancer-associated fibroblasts (CAFs)." (PMID 27596051, 2016). "We identified more novel interacted proteins with PIM kinases (PIM1, PIM2 and PIM3) and further shed light on more molecular mechanisms of PIM kinases in cancer." (PMID 25749522, 2015). "Taken together, PIM1 is up-regulated by hypoxia in HCC and promotes tumor growth and metastasis through facilitating cancer cell glycolysis." (PMID 25834102, 2015). "Therefore, targeting Pim-1 may provide a new therapeutic approach for the cancers." (PMID 25342548, 2014). "Our study now demonstrated upregulation of Pim-1 expression at the mRNA and protein levels with EBV infection in primary B-cells as well as EBV positive cancer cell lines." (PMID 25121590, 2014). "This study provided new data of Pim-1 activity in ACC and is suggestive that Pim-1 has potential to become a tumor marker as well as a therapy target of cancer." (PMID 25551195, 2014). "Our findings support the targeting of Pim1 in human cancer and suggest a potential for using the same inhibitor (such as 10058-F4) to target both MYC and PIM1 in human tumors." (PMID 20515470, 2010). "Many of the genes, identified in this study as the potential targets of differentially regulated miRNAs are known to be involved in cancer through their effects on cell differentiation (CDK6, LIFR), apoptosis (PIM1) or hematopoiesis (GATA2, TAL1)." (PMID 20459673, 2010). "We decided to investigate how the replacement of the benzene ring with a small methyl substituent and a slight modification of the alkyl chain between the TBBi scaffold and the carbonyl group would affect the anti-cancer properties and affinity of the compounds for CK2 and PIM-1." (PMID 40565356, 2025).